ELMO1 (engulfment and cell motility 1)
Diseases named in the same sentence as ELMO1 in open-access papers (continued):
Sharing a sentence is not in itself a finding about the gene and the disease.
Immunodeficiency (1 paper, 2021). Failure of the immune system to protect the body adequately from infection, due to the absence or insufficiency of some component process or substance. "Whether ELMO1 mutation could lead to immunodeficiency in human warrants further study." (PMID 34993193, 2021).
kidney failure (1 paper, 2023). An acute or chronic condition that is characterized by the inability of the kidneys to adequately filter the blood. "The studies here may have important implications for targeting ELMO1 to inhibit the infiltration of neutrophils into the peritoneum, which may help patients with kidney failure." (PMID 37175809, 2023).
liver cancer (1 paper, 2023). An epithelial or non-epithelial malignant neoplasm that arises from the liver. "Subsequently, NPM1 translocated from the nucleus to the cytoplasm and plasma, where it interacted with ELMO1, activated small GTPases (Rac1), and ultimately triggered actin polymerisation and liver cancer cell migration." (PMID 37251542, 2023).
malignant glioma (1 paper, 2017). A grade III or grade IV glioma arising from the central nervous system. "Engulfment and cell motility 1 (ELMO1) plays a role in promoting cancer cell migration and invasion in malignant glioma." (PMID 28418867, 2017).
metabolic bone disorder (1 paper, 2021). A group of disorders that affect the bones secondary to increased levels of minerals or deficient levels of minerals such as calcium, magnesium, phosphorus, and vitamin D. Representative examples are osteomalacia, osteoporosis, and Paget disease. "Further studies would shed light on the functions and mechanisms of ELMO1 in regulating bone resorption, which may lead to new therapeutic strategies for the treatment of diseases related to metabolic bone disorders." (PMID 34381782, 2021).
peritonitis (1 paper, 2023). Inflammation of the peritoneum (tissue that lines the abdominal wall and covers most of the organs in the abdomen). "The results reported herein show that ELMO1 plays a role in the recruitment of neutrophils in a mouse model of TG-induced peritonitis." (PMID 37175809, 2023). "More importantly, we found that peritoneal inflammation is alleviated in Elmo1 knockout mice in the mouse model of thioglycollate (TG)-induced peritonitis." (PMID 37175809, 2023). "We found that inflammation was alleviated in Elmo1 knockout mice in the mouse model of TG-induced peritonitis." (PMID 37175809, 2023). "To study the possible role of ELMO1 in the inflammatory response, we successfully constructed an acute peritonitis model using 4% TG in Elmo1−/− and Elmo1+/+ adult mice." (PMID 37175809, 2023). "The results presented here reveal the biological functions of ELMO1 in the chemotaxis of neutrophils in murine peritonitis." (PMID 37175809, 2023). "Importantly, we also reveal that peritoneal inflammation is alleviated in Elmo1 knockout mice in the mouse model of thioglycollate-induced peritonitis." (PMID 37175809, 2023). "Our results suggest that the targeted inhibition of ELMO1 may pave the way for the design of novel anti-inflammatory therapies for peritonitis." (PMID 37175809, 2023). "However, the role and mechanism of ELMO1 in regulating the chemotaxis of neutrophils in acute peritonitis remains unclear." (PMID 37175809, 2023).
polycystic kidneys (1 paper, 2016). "In human samples, immunohistochemical staining of ELMO1 in nondiabetic, diabetic and polycystic kidneys localized ELMO1 in glomerular podocytes and in the tubules." (PMID 27849017, 2016). "ELMO1 expression was analysed for potential changes within human kidney sections received from nondiabetic, diabetic (type 2) and polycystic kidney disease patients." (PMID 27849017, 2016). "This coincides with our data from type 2 diabetic patients, where no change in ELMO1 expression was observed within the kidney, compared to nondiabetic and polycystic kidneys, respectively." (PMID 27849017, 2016). "Hence, kidney sections from nondiabetic, diabetic and polycystic kidney disease patients were tested for ELMO1 expression." (PMID 27849017, 2016).
preeclampsia (1 paper, 2024). Preeclampsia is a hypertensive disorder of pregnancy that is characterized by new-onset hypertension with proteinuria presenting after 20 weeks of gestation, and depending on mild or severe forms may initially present with severe headache, visual disturbances, and hyperreflexia. "Several hub genes, including ELMO1, YWHAE, and IL6ST, were significantly reduced in the placental vessels in preeclampsia." (PMID 39600942, 2024).
respiratory failure (1 paper, 2022). The significant impairment of gas exchange within the lungs resulting in hypoxia, hypercarbia, or both, to the extent that organ tissue perfusion is severely compromised. "We found that mice lacking both ELMO1 (globally) and ELMO2 (muscle specific) died at birth, and we speculate that this is secondary to respiratory failure as a result of poorly developed muscles." (PMID 36400788, 2022).
spondyloarthritis (1 paper, 2021). "Higher ELMO1 expression of AS-MSC is found in vivo in AS patients, and inhibiting ELMO1 in SKG mice produces therapeutic effects in this spondyloarthritis model." (PMID 34508078, 2021). "Moreover, injecting Av-ELMO1 significantly improved inflammation and ectopic ossification in SKG mice serving as a spondyloarthritis model." (PMID 34508078, 2021).
squamous cell carcinoma (1 paper, 2017). A carcinoma arising from squamous epithelial cells. "Knocking down Elmo1 impairs metastasis of carcinoma cells to the lung, thereby providing insights into the mechanisms of progression of Tgfbr2-deficient invasive transition zone squamous cell carcinoma." (PMID 28219480, 2017).
systemic sclerosis (1 paper, 2022). A chronic disorder, possibly autoimmune, marked by excessive production of collagen which results in hardening and thickening of body tissues. "Of the variants identified by 3DFAACTS-SNP, one variant (rs60600003) located at a locus on chromosome 7 was found to be associated with several diseases, including MS, celiac and systemic sclerosis, suggesting its interacting gene, ELMO1, may contribute to a common Treg defect in these diseases." (PMID 35773720, 2022).
cancer (17 papers, 2010 to 2025). A tumor composed of atypical neoplastic, often pleomorphic cells that invade other tissues. "The impairment of the TGFβ receptor II (Tgfbr2) causes cancer cell metastasis and invasion via ELMO1 repression." (PMID 36146567, 2022). "ELMO1 has also been found to be associated with cancer development by regulating cancer cell proliferation, chemotaxis and invasiveness." (PMID 36358701, 2022). "Because aberrant activation of cell motility pathways may underlie the variety in cancer cell invasion, the elucidation of mechanisms underlying ELMO1 pY724-mediated promotion in Rac activity might establish these molecules as potential targets for effective cancer therapies." (PMID 26205662, 2015). "One other smaller study which adjusted for mucinous type and location only investigated methylation in ELMO1 along with other epigenetic markers in a panel and found worse prognosis in KRAS mutated cancers." (PMID 31340858, 2019). "This corresponds well with previous findings from other types of cancer, where promoter hyper- and hypomethylation have been observed in a subset of cases for ELMO1 and ELMO3, respectively." (PMID 29495584, 2018). "Ephexin4, a guanine nucleotide-exchange factor for RhoG, promotes engulfment of apoptotic cells and cancer cell migration in a RhoG-dependent manner, which is synergistically augmented by Elmo1, an Ephexin4-interacting protein." (PMID 28667327, 2017). "Therefore, we can fully understand the value of ELMO1, which regulates cancer metastasis and requires investigation in further studies on solid tumours." (PMID 37251542, 2023). "The impairment of ELMO1 decreases the metastasis of the cancer cells." (PMID 36146567, 2022). "DNA methylation changes in gene promoter CpG islands are responsible for altering the expression of many different tumor suppressor genes and oncogenes in cancer, including ELMO1 in gastric cancer and ELMO3 in lung adenocarcinoma, and associated brain metastases." (PMID 29495584, 2018). "The complex of Dock180/ELMO1 that functions as a bipartite guanine nucleotide exchange factor for Rac is essential for diverse physiological and pathological processes of cells such as cell migration, phagocytosis, and invasion of cancer cells." (PMID 26205662, 2015). "As the overexpression and/or hyperactivation of Src have been shown in a wide variety of human cancers, Src-mediated phosphorylation of Y724 in ELMO1 may regulate cancer cell adhesion to the ECM, invasion into surrounding tissues, and subsequent distant metastasis." (PMID 26205662, 2015). "As the overexpression and/or hyperactivation of Src have been shown in a wide variety of human cancers, Src-mediated phosphorylation of Y724 in ELMO1 may regulate cancer cell adhesion to the extracellular matrix, invasion into surrounding tissues, and subsequent distant metastasis." (PMID 26205662, 2015). "Although the methylation levels of ELMO1, ZNF582 and TFPI2 all showed a significant difference between each cancer type and control subjects, they still showed a preference for a certain cancer type." (PMID 36358701, 2022). "As Src has been reported to be overexpressed in several human cancers, we focused on Src and examined whether Src directly phosphorylates ELMO1 by in vitro kinase assay using GST-ELMO1 as a substrate." (PMID 26205662, 2015). "However, the role and regulating mechanism of EMLO3 remains unclear compared with those of ELMO1 and ELMO2, which present unique and overlapping functions in different types of cancer." (PMID 27999268, 2016). "ELMO1 and ELMO2 are highly expressed in most human cancer tissues, whereas ELMO3 is only found in some cancer tissues, and its function has not been fully clarified in GC." (PMID 30345300, 2018).
infection (11 papers, 2012 to 2025). The state of being infected such as from the introduction of a foreign agent such as serum, vaccine, antigenic substance or organism. "Among the various pathways and functions that are controlled by ELMO1 during SL and SifA mutant infection, most of these pathways are associated with metabolism and host immune/defense responses." (PMID 41250600, 2025). "The bacterial burden and weight loss were slightly higher in WT mice compared to ELMO1 KO mice in WT SL infection (SupplementaryFigure 3A-E)." (PMID 34719317, 2021). "Five days after infection, the percentage of weight loss was significantly higher in WT mice compared to ELMO1 KO mice infected with WT SL, and higher weight loss was recorded in mice infected with WT SL compared to the littermates infected with the sifA mutant." (PMID 34719317, 2021). "To validate the proteomics data and the effect of ELMO1 on the identified proteins, we performed in vitro and in vivo infection experiments and assessed the expression of selected proteins via western blotting." (PMID 41250600, 2025). "Gene ontology enrichment analysis revealed 19 upregulated and 11 downregulated proteins exclusive to ELMO1-depleted cells during infection, belonging to mitochondrial functions, metabolism, vesicle transport, and the immune system." (PMID 41250600, 2025). "We also identified the differential proteome profile after infection of ELMO1-depleted macrophages with WT SL and SifA -mutant Salmonella." (PMID 41250600, 2025). "Next, we checked the effects of ELMO1 and SifA in pair 9 SifA mutant infection of C1 and E1 cells and in pair 10 with E1 SifA vs C1 SL." (PMID 41250600, 2025). "Like our previous study and as shown inFigure 3(b), ELMO1 KO ileum EDMs had lower number of internalized bacteria after 3h of infection, as compared to both WT and NOD2 KO ileum EDMs." (PMID 36694274, 2023). "The infection of murine EDMs with AIEC-LF82 showed higher bacterial load in ELMO1-KO, NOD2 KO EDMs, and ELMO1 KO EDMs treated with NOD2 inhibitors." (PMID 36694274, 2023). "Previously, we had reported that ELMO1 regulated the immune response against infection in macrophages by producing pro-inflammatory cytokines." (PMID 36694274, 2023). "Although a smaller number of bacteria entered in ELMO1 KO cells, the bacterial count was higher at 12 h of infection as compared to WT ileum EDMs, depicting prolonged survival and delayed clearance." (PMID 36694274, 2023). "Further, ELMO1 KO mice showed reduced colonic inflammation and pro-inflammatory cytokines following intestinal pathogen infection." (PMID 36694274, 2023). "The amount of active Rac1 was higher after infection with WT SL in control shRNA cells compared to ELMO1 shRNA cells." (PMID 34719317, 2021). "Next, we assessed the relevance of ELMO1 and SifA interaction in the early phase of infection (infection by gavage for 2 days) in WT and global ELMO1 KO mice." (PMID 34719317, 2021). "Since ELMO1 is crucial for bacterial internalization and the induction of inflammatory response, infection with WT Salmonella was more attenuated in ELMO1 KO mice." (PMID 34719317, 2021). "The expression of inflammatory cytokines was significantly reduced in mice infected with the sifA mutant compared to WT SL infected mice, with much decrease in the levels of these transcripts in ELMO1 KO mice compared with the WT mice in both infections." (PMID 34719317, 2021). "Increased transcription of Elmo1 following miR-206 knockdown is likely to increase neutrophil mobility during infection in cooperation with increased Cxcl12/Cxcr4 signalling." (PMID 33826679, 2021). "Overall, the degree of infection and inflammation was lower in mice infected with the sifA mutant, and it was the lowest in ELMO1 KO mice infected with the sifA mutant." (PMID 34719317, 2021).
infection (continued). "To examine the involvement of c-Maf, Bach-1, and Elmo-1 in Mtb-growth promotion within M(IL-4/IL-13) BMDMs, we knocked-down these target genes using GapmeRs in M(IL-4/IL-13) BMDMs prior to infection with Mtb." (PMID 30941122, 2019). "To understand whether the role of ELMO1 is linked to the function of DRP1, we used the DRP1 inhibitor Mdivi−154 in C1 and E1 cells following infection with SL for 3 h and 6 h." (PMID 41250600, 2025). "Similar to ELMO1 deficient EDMs, NOD2 KO EDMs and ELMO1 KO EDMs treated with GSK717 also had a defect in bacterial internalization, and a delayed clearance of bacteria thus leading to higher load after 12 h of infection." (PMID 36694274, 2023). "Similarly, to evaluate the influence of ELMO1 and NOD2 interaction, we quantified the levels of pro-inflammatory cytokines in macrophages upon infection with CD-associated AIEC-LF82." (PMID 36694274, 2023). "Using WT and ELMO1 KO mice (global KO and myeloid cell-specific ELMO1 KO) challenged with WT Salmonella or the sifA mutant, we found that the infection was less severe in ELMO1 KO mice, particularly in mice infected with the sifA mutant compared to WT Salmonella." (PMID 34719317, 2021). "Furthermore, many chemokine receptors like CCR4, CCL14, XCR1 along with the adaptor molecules CRKII and ELMO1 were downregulated during initial and mid stages of infection, and in contrast, some G protein signaling molecules such as GNAI, GNB1, FAK and FAK2 were upregulated in infected fish." (PMID 33177569, 2020). "Importantly, we observed that the changes induced by SL are exacerbated by the depletion of ELMO1, as reflected by the increased percentage of glycolysis and a further reduction in the percentage of oxidative phosphorylation in E1 cells compared to C1 macrophages during SL infection." (PMID 41250600, 2025). "The level of TNF-α was increased with infection, and it was significantly higher in control (C1) cells transfected with SifA, IpGB1, IpGB2, and/or MAP compared to ELMO1 (E1) shRNA cells." (PMID 34719317, 2021). "Here, we determined the DEPs after Salmonella effector protein SifA during infection in the presence or absence of ELMO1." (PMID 41250600, 2025). "In AIEC-LF82 infection, the absence of either ELMO1 or NOD2 or both resulted in a significant decline in IL-6 levels compared to C1 cells." (PMID 36694274, 2023). "To assess the impact of NOD2 on the integrity of gut barrier following infection, we challenged EDMs from WT, ELMO1 KO and NOD2 KO mice with AIEC-LF82 infection and then assessed the gut barrier integrity by measuring the transepithelial electrical resistance (TEER)." (PMID 36694274, 2023). "Infection of the cells with the pLVX-mCherry vector did not affect the efficiency of the shRNA, as we observed a similar reduction in Elmo1 mRNA compared to CD34+ cells isolated from SH02 tumors that did not express the mCherry (50% reduction for construct #1 and 60% reduction for construct #2." (PMID 28219480, 2017).
tumor (11 papers, 2015 to 2025). "Studies have shown that IL-8 can escalate tumor metastasis by upregulating the expression of ELMO1 in tumor cells." (PMID 32161718, 2020). "Engulfment and cell motility 1 (ELMO1) is an evolutionarily conservative protein expressed in tumor cells that mainly mediates cell phagocytosis, migration, and morphological changes." (PMID 32161718, 2020). "We confirmed that the GEF ELMO1 is co-expressed with CD34-positive tumor epithelial cells at the protein level by immunofluorescence staining and observed increased staining of this RAC-activating factor at the leading edge of the tumor." (PMID 28219480, 2017). "ELMO1/Dock180 complex is implicated in pathogenesis of various diseases such as diabetic nephropathy, HIV infection, and tumor development." (PMID 26205662, 2015). "Furthermore, the DMF significantly inhibited tumour metastasis induced by the NPM1/ELMO1 signalling pathway, as observed in in vitro cell functional experiments." (PMID 37251542, 2023). "Furthermore, tumor metastasis is supported by IL-8 secretion through the upregulation of engulfment and cell motility 1 (ELMO1) expression, a tumor-expressed protein involved in cell migration, phagocytosis, and morphological changes." (PMID 37958467, 2023). "The expression level of ELMO1 was significantly related with higher tumor grade (P = 0.008)." (PMID 33747931, 2021). "In addition to taking part in physiological processes, ELMO1 is involved in pathological conditions such as tumor invasion and local inflammation when abnormally expressed." (PMID 34508078, 2021). "However, tendencies were observed that patients with an ELMO1 hypermethylated tumor were unmethylated at the MGMT promoter (p = 0.053), and likewise that patients with an ELMO3 hypomethylated tumor were unmethylated at the MGMT promoter (p = 0.137)." (PMID 29495584, 2018). "Among them, two significantly mutated genes are ELMO1 and DOCK2, encoding dimerization partners and intracellular mediators of the Rho family; ELMO1 or DOCK2 are mutated in 17% of cases, and their mutation determines an enhancement of cellular motility and favors tumor invasion." (PMID 28930282, 2017). "As these extrinsic factors could induce the activation of Src, they might also enhance migration of tumor cells through possible Y724 phosphorylation of ELMO1." (PMID 26205662, 2015). "The promoter methylation levels of ELMO1 and ELMO2 were generally low, whereas ELMO3 methylation levels were high, in the tumor biopsies." (PMID 29495584, 2018). "The mean ELMO1, ELMO2, and ELMO3 methylation levels in the tumor biopsies were 6.8% (SD 3.9), 3.3% (SD 2.6), and 80.6% (SD 13.0), respectively." (PMID 29495584, 2018). "To determine whether Elmo1 knockdown altered tumor progression and metastasis in Tgfbr2 cKO SCC, we screened the lungs of tumor-bearing mice for YFP+ metastases by FACS." (PMID 28219480, 2017).
bacterial infection (2 papers, 2021 to 2023). "Since ELMO1 and NOD2 regulate intestinal immune response against bacterial infections, we assessed if ELMO1 and NOD2 could interact physiologically." (PMID 36694274, 2023).